BRD4 (bromodomain containing 4)
Diseases named in the same sentence as BRD4 in open-access papers (continued):
Sharing a sentence is not in itself a finding about the gene and the disease.
cancer (continued). "ARV‐825 induced apoptosis, inhibited cell proliferation, and reduced c‐Myc expression, a key BRD4 target involved in cancer progression." (PMID 39898116, 2025). "The uniform expression of ROR1 in cancer, along with its internalization capability and strong correlation with BRD4, makes it a promising target for conjugation." (PMID 39816690, 2025). "Another approach to block BRD4 function in cancer cells is represented by the use of “PROteolysis-TArgeting Chimeras”, or “PROTACs”." (PMID 41311847, 2025). "The BRD4 inhibitor JQ1 can trigger ferroptosis in apoptosis-resistant cancer cells, augmenting the anticancer efficacy with ferroptosis inducers." (PMID 40327848, 2025). "A CRISPR-Cas9 cell line model validates that fine-tuned BRD4 expression is required for cancer cell growth." (PMID 40112818, 2025). "BRD4, a pleiotropic regulator of chromatin structure and transcription, plays critical roles in cancer and immune responses." (PMID 40970132, 2025). "JQ1, a small molecule inhibitor of BRD4, has shown promise in preclinical models of inflammatory diseases and cancers." (PMID 40616163, 2025). "For example, a PROTAC targeting BRD4 restored doxorubicin sensitivity in resistant cancer cells and is of potential use in combination therapies." (PMID 39898116, 2025). "BRD4 has emerged as a potential therapeutic target for a range of human diseases, including cancers, gastrointestinal diseases, and cardiovascular diseases." (PMID 41280641, 2025). "BRD4 is recruited to superenhancers and consequently functions as an epigenetic reader to promote transcription of superenhancer-marked genes in cancer cells." (PMID 41311847, 2025). "Recently, JQ1 has been shown to ultimately enhance intracellular LLPS, presumably due to the compensatory BRD4 overexpression, which limits its applicability in both basic studies and cancer therapy." (PMID 40744496, 2025). "Targeting epigenetic regulators such as BET proteins (e.g., BRD4) has emerged as a powerful therapeutic strategy for cancer treatment." (PMID 39119816, 2025). "Small chemical JQ1 is cell permeable and can attach to BRD4 fusion oncoproteins, like BRD4-NUT, in a competitive manner, which causes cancer cells to differentiate and undergo apoptosis." (PMID 40581650, 2025). "As expected, we found a patient-dependent cancer cells death in response to JQ1 treatment correlating with a heterogeneous expression of BRD4 in PDSES." (PMID 39774014, 2025). "Bromodomain and outdomain (BET) proteins, mainly composed of BRD2, BRD3, and BRD4 proteins, function as epigenetic readers and transcription coactivators and are currently recognized as therapeutic cancer targets." (PMID 41049615, 2025). "On the other hand, BRD4, as an epigenetic reading and cancer therapeutic target, has a controversial role in ferroptosis, but studies have shown that BRD4 inhibition has a significant effect on ferroptosis." (PMID 40143112, 2025). "Taken together, BRD4 inhibition mediates improved immune function in the setting of cancer via its inhibitory effects on MDSCs and the resulting release of T cell inhibition." (PMID 40762981, 2025). "The role of BET proteins—particularly BRD4—as global transcriptional regulators is well established in cancer and inflammatory diseases." (PMID 41226402, 2025). "From this effort, focal SVs within the bromodomain-containing protein 4 (BRD4) in chromosome 19p were detected in a fraction of ovarian (n = 8) and breast (n = 7) cancers, occurring primarily in tumors with amplifications spanning the BRD4 locus." (PMID 40112818, 2025).
cancer (continued). "In 10/16 cell lines (62.5%), global BRD4 overexpression decreased cell growth (as evidenced by negative log-fold changes), supporting its role as a “toxic” gene in cancer." (PMID 40112818, 2025). "Tumor BRD4 gene expression was quantified using RNA-Seq across pan-cancer datasets from 189 human cancer studies by the Liu group." (PMID 40762981, 2025). "Research has shown that inhibiting the activity of BRD4 can modulate the DNA damage response, thereby increasing the sensitivity of cancer cells to stress-inducing agents." (PMID 40083325, 2025). "BRD4 is believed to be a promising anti-cancer drug target due to its strong positive effects on the expression of the transcription factor MYC, which is a well-known oncogenic master regulator and a driver of colon tumorigenesis." (PMID 41311847, 2025). "The 8QAR protein can interfere with BRD4’s activity, potentially reducing the proliferation of cancer cells." (PMID 41323392, 2025). "The transcriptional outcomes of BRD4 inhibition determine the sensitivity of cancer cells to BET inhibitors." (PMID 41249136, 2025). "Blocking the activity of BRD4 has recently been recognized as a potentially effective approach to treat cancer." (PMID 39941011, 2025). "BMS-986158, a highly selective and potent inhibitor of BRD2/BRD4, has demonstrated anti-cancer activity through the downregulation of BRD4 and c-MYC expressions in preclinical efficacy studies and a clinical trial for patients with solid tumors (NCT02419417)." (PMID 40937321, 2025). "As a transcriptional and epigenetic regulator, bromodomain protein 4 (BRD4) plays a key role in cancer initiation and development." (PMID 41184230, 2025). "BRD4 is crucial for the expression of genes that promote cell growth and survival, making it an attractive target for cancer therapy." (PMID 39851497, 2025). "The rational design of JQ1 as a competitive inhibitor of Bromodomain Containing Protein 4 (BRD4) opened the avenue for molecularly-targeted therapeutic agents geared towards epigenetic reader proteins with key roles in homeostasis and cancer." (PMID 38539439, 2024). "Immunohistochemical analysis of PDX tumors confirmed that BRD4 was degraded by 84-EBET on both cancer and stromal cells in the tumors, suggesting that EBET diffused from the cancer cells had a bystander effect on CEACAM6-negative stromal cells." (PMID 38467634, 2024). "The MYC proto-oncogene and bromodomain-containing protein 4 (BRD4) exert their effects by modifying the expression of key cancer-related genes." (PMID 39335515, 2024). "For example, in silico analyses were performed for some alternatively spliced proteins with reported antagonistic functions in cancer, including BRD4, KLF4, and UHRF2." (PMID 38539439, 2024). "JQ-1, an inhibitor of BRD4, was found to promote ferroptosis of cancer cells and inhibit tumor development." (PMID 38565708, 2024). "BRD4 is a well-established target for intervention in diseases such as cancer and immune-related inflammation, so the development of BRD4 inhibitors has reached a relatively advanced stage." (PMID 39349832, 2024). "The findings reveal that the effects of the BRD4 inhibitors on OAd replication, oncogene expression, and inhibition of inflammatory pathways contribute to the increased cancer cell killing and amplified viral replication in PDAC models." (PMID 38279262, 2024). "It has been proved that bromodomain containing protein 4 (BRD4) recruits NF-κB p65 to form SEs on cancer stem gene, and their destruction can effectively inhibit the invasion and metastasis of CSCs." (PMID 38561775, 2024). "By specifically targeting BRD4 for degradation within cancer cells during PDT treatment, NGP-65 provides a promising strategy for improving clinical outcomes in tumor therapy." (PMID 38773495, 2024).
cancer (continued). "This role is particularly significant in the context of cancer, where BRD4 is frequently overexpressed and interacts with E2F transcription factors to regulate genes crucial for cell cycle progression and DNA replication." (PMID 39066258, 2024). "BRD4 is a transcriptional and epigenetic regulator that plays a pivotal role in embryogenesis and cancer development." (PMID 38229152, 2024). "Collectively, these elements contribute to the constrained effectiveness of BRD4 inhibitors in the realm of cancer therapy." (PMID 38365636, 2024). "BRD4 is considered a universal transcriptional regulator with enrichment on super-enhancers that drive the expression of cancer-specific genes." (PMID 38225241, 2024). "JQ1, a commonly used inhibitor of BRD4 in preclinical research, hinders the binding of BRD4 to acetylated histones, thereby exerting anti-cancer effects both in vitro and in vivo." (PMID 38443991, 2024). "BRD4 is unevenly distributed within cancer cells, with higher concentrations observed for some important oncogenes, such as c-Myc." (PMID 38473320, 2024). "Through analyzing hundreds of NC GEMM, our data demonstrated that when expressed at the endogenous level from an endogenous chromosome translocation, Brd4::Nutm1 can efficiently induce aggressive cancers with high penetrance." (PMID 38724194, 2024). "The application of NGP-34 has shown promising results in inducing specific degradation of BRD4 protein in various cancer cell lines." (PMID 38773495, 2024). "Together, these results suggest that in cancer cells, REV-ERBα switches its cofactor association from the corepressors to coactivator BRD4 and p300 to directly activate tumorigenic gene programs." (PMID 39383000, 2024). "BRD4 inhibitors have great potential to promote ferroptosis in cells, especially in cancer cells treated with erastin." (PMID 38565708, 2024). "The correlation between YAP1 and BRD4 protein was obtained using Spearman correlation test across 33 cancer types." (PMID 38169595, 2024). "Bromodomain and extra-terminal (BET) proteins (BRD2, BRD3, and BRD4) play a multifaceted role in cancer biology, as they can exert their influence through several mechanisms." (PMID 38201308, 2024). "The levels of GPX4, SLC7A11, and SLC3A2 were reduced in cancer cells treated with either BRD4 knockout or JQ-1." (PMID 38565708, 2024). "Inhibiting BRD4 can disrupt the communication between SEs and promoters, effectively suppressing the transcription and expression of oncogenes, reducing cancer cell proliferation and viability." (PMID 39156700, 2024). "BRD4 is required for cell proliferation and mitosis, and thus its dysregulation is frequently involved in cancer." (PMID 38617536, 2024). "This comprehensive regulatory role makes BRD4 a key therapeutic target, especially in oncology, where the modulation of transcription can influence cancer progression and treatment outcomes." (PMID 39066258, 2024). "JQ1 inhibits the abnormal expression of cancer related lncRNAs and mRNAs by blocking the interaction between BRD4 and eRNAs, thereby exerting anti-tumor effects (Duan, Yu & Chen, 2023)." (PMID 38410799, 2024). "Among the BET protein family, BRD4 has emerged as a promising therapeutic target for various cancers." (PMID 39770515, 2024). "So far, divergent biological roles of BRD4 isoforms in transcription regulation, DNA damage response and cancer progression have been reported." (PMID 38874522, 2024). "This method has been validated through Western blot assays and cytotoxicity experiments that demonstrate its effectiveness in degrading BRD4 more effectively and being more cytotoxic in H2O2-rich cancer cells than in H2O2-deficient normal ones." (PMID 38773495, 2024).
cancer (continued). "Approximately 50 trials have been completed or are in phase 1.Clinical studies on BET inhibitors have validated BRD4 as a drug target for cancer and other indications." (PMID 38473997, 2024). "A second case had been discovered in a large series of pediatric cancers where the BRD4::LEUTX fusion had been identified in one case of the series." (PMID 38500181, 2024). "Recent evidence from nine adult cancer cell lines has shown that BRD4 inhibitors can be used to convert MMR-proficient (pMMR) tumors into MMR-deficient (dMMR) tumors by decreasing the expression level of key MMR genes." (PMID 39766049, 2024). "It is evident that there remains a substantial scope for further understanding the implications of BRD4 in the context of cancer." (PMID 38473320, 2024). "In cancer cells, BRD4 regulates the expression of oncogenic gene c-MYC and DNA damage response factors." (PMID 38669046, 2024). "Bromodomain-containing protein 4 (BRD4) is an epigenetic reader and a promising target for cancer therapeutics." (PMID 38565708, 2024). "In studies focusing on cancer-cell types, it has been demonstrated that BET inhibitors, such as JQ1, which target the bromodomain reader protein Brd4, can lead to decreased expression of SE-associated oncogenes." (PMID 38542080, 2024). "Continued research into BRD4’s diverse functions promises new therapeutic strategies targeting its activity in cancer and other diseases with genomic instability." (PMID 39066258, 2024). "The importance of the BRD4 BD1 domain extends into the realm of disease, where its dysregulation has been linked to a spectrum of disorders, most notably cancer and inflammatory diseases." (PMID 39458928, 2024). "SNIPERs have worked well not only in cancer targets (e.g., targeting estrogen receptor α (ERα), bromodomain-containing protein 4 (BRD4)) but also in immune diseases and neurodegenerative disease targets, such as mutant tau and Htt." (PMID 38474412, 2024). "This active PROTAC specifically targets BRD4, which plays a crucial role in cancer cell growth and survival." (PMID 38773495, 2024). "The small molecule BRD4 leads to dysregulated gene expression and promotion of cancer cell survival and proliferation." (PMID 38473320, 2024). "METTL3 has been shown to interact directly with BRD4, a vital transcriptional regulator that plays an essential role in gene expression in cancer cells." (PMID 39335515, 2024). "In various cancers, including leukemia, breast, and prostate cancers, aberrant activity or overexpression of BRD4 has been observed to drive the transcription of oncogenes like MYC and BCL-2." (PMID 39458928, 2024). "The elevated expression of BRD2/BRD3/BRD4/YAP1 is a risk factor from the Cox cross-pan-cancer dataset proportional hazards model in a variety of tumors, including SKCM, besides, there was an association between BRD4 and YAP1." (PMID 38169595, 2024). "BRD4, the most frequently studied bromodomain in cancer research, recruits transcription factors essential for RNA polymerase II-dependent transcription." (PMID 39766049, 2024). "Further research is necessary to fully elucidate the intricate interplay between METTL3, Pin1, and BRD4 in the context of various cancers." (PMID 39335515, 2024). "JQ-1, a BRD4 inhibitor, has been verified to repress tumor growth by inducing direct cell death and indirect immune activation in multiple human cancer cells." (PMID 38203835, 2024). "The subtype and cancer-specific roles underscore the need to systematically dissect BRD4 isoform-specific functions and BET protein functions for precision targeting in disease therapy." (PMID 38191874, 2024). "BRD4 inhibitors constitute a category of small-molecule compounds that exhibit the potential to significantly enhance cancer treatment by mimicking the effects of acetyl-lysine." (PMID 38365636, 2024). "The consistent induction of poorly differentiated carcinoma demonstrated a strong reprogramming activity of BRD4::NUTM1." (PMID 38724194, 2024).
cancer (continued). "N-terminal bromodomain (BD1) is essential for disrupting BRD4 interactions and is a promising protein for cancer therapy." (PMID 37570684, 2023). "JQ1 exhibits a potent antiproliferative effect in Brd4-dependent cancer cells lines and against NMC." (PMID 37049806, 2023). "It is desirable to establish the clinical benefit of Brd4-selective BET inhibitors over pan-BET inhibitors in individual cancer types." (PMID 37049806, 2023). "The scientists reported that blocking Brd4 decreases Myc and prevents cancer cell proliferation, and that Brd4 binds to a 40000-bp stretch near the MYC gene." (PMID 37190100, 2023). "The trastuzumab on the particle surface notably enhanced the internalization of the nanoparticles to HER2-expressing cancer cells, and the endocytosed MZ1 brought into their BRD4 deficiency-associated apoptosis." (PMID 36839734, 2023). "The synergistic effect of TOP1 + BRD4 inhibition is specific to cancer cells leaving normal cells unaffected, highlighting the tumor’s vulnerability to transcriptional defects." (PMID 37831776, 2023). "Although BRD4 was initially recognized for its involvement in cancer progression, its significance has been found in many other diseases, such as heart disease and infectious diseases." (PMID 37509171, 2023). "BRD4 also promotes stemness in cancers of other types, including breast, gastric, esophageal, or prostate tumors." (PMID 36674511, 2023). "Subsequent investigations have shown the significant involvement of BET proteins, particularly BRD4, in the pathogenesis and advancement of cancer." (PMID 37926722, 2023). "The human ortholog BRD4 has pro-cancer properties, and it is commonly used as a target for anti-cancer therapy." (PMID 37204421, 2023). "BRD4 has attracted attention as a promising anti-cancer drug target due to its strong effect on expression of the transcription factor MYC, which is a well-known pro-oncogenic master regulator and a major driver of wide variety of cancers." (PMID 36711038, 2023). "As the most widely studied member, BRD4 has emerged as an attractive therapeutic target for cancer therapy." (PMID 36733715, 2023). "In summary, the interplay between transcriptional elongation, RNAPII, BRD4, and cancer is a dynamic and intricate process." (PMID 38201534, 2023). "BRD4 is widely recognized in cancer due to its role in super-enhancer (SE) tissue and oncogene expression regulation." (PMID 37446009, 2023). "Inhibition of BRD4 promotes both anti-cancer and senolytic outcomes, which provides the first potential drug target to tackle both problems simultaneously (right)." (PMID 37204421, 2023). "After their endocytosis to cancer cells, the bonds between PROTACs and trastuzumabs were hydrolyzed to release free PROTACs, inducing irreversible BRD4 degradation." (PMID 36839734, 2023). "Dual Brd4-tyrosine kinase inhibitors were designed to specifically target cancers that depend on Brd4 functionality and aberrant oncogenic kinase activity." (PMID 37049806, 2023). "After the treatment of ARNIPL to 3D cancer spheroids, ARV-825 induced the BRD4 depletion-associated down-regulation of c-Myc, and nintedanib inhibited the transforming growth factor beta 1 (TGF-β1), resulting in synergistic antitumor efficacy." (PMID 36839734, 2023). "MZ1 was the first PROTAC drug developed, with active ligands at both ends linked to the ubiquitin ligase von Hippel–Lindau (VHL) and the bromodomain and extra-terminal domain family protein bromodomain-containing protein 4 (BRD4) for cancer treatment." (PMID 36872349, 2023). "Studies have reported that BRD4 inhibitors treat cancer by interfering with the interaction between BRD4 and acetyl lysine on target proteins." (PMID 36793283, 2023). "Recent studies have shown that this compound can inhibit PI3K/AKT/mTOR and bromodomain-containing protein 4 (BRD4) pathways in cancer cells." (PMID 37046703, 2023).